CEACAM5 (CEA cell adhesion molecule 5)
Diseases named in the same sentence as CEACAM5 in open-access papers (continued):
Sharing a sentence is not in itself a finding about the gene and the disease.
tumor (continued). "Additionally, a malignant-enriched cluster that was mostly derived from LUAD specimens clustered distinctly from cells of uninvolved lung tissues and exhibited high expression of tumor markers (e.g., CEACAM5), as well as comprised mixed-lineage genes in line with previous studies." (PMID 33809063, 2021). "Moreover, while KLK6 and SLC35D3 were CC-tumor specific in the sense that only CC tumor tissue expressed the biomarkers compared to normal colon tissue or normal colon epithelial cells, CEACAM5 and MUC2 were expressed at approximately the same levels in normal and cancerous colon tissues." (PMID 32049988, 2020). "However, the TCGA expression results raise the possibility that elevated CEACAM5 in plasma may precede tumor metastasis." (PMID 33004987, 2020). "Thus, at various stages during tumor dissemination some CEACAM5-competent cells may benefit from upregulating CEACAM5 by differentiating or undergoing MET." (PMID 33196697, 2020). "In addition, a minor population of tumor cells exhibited co-staining for both CEACAM5 and vimentin." (PMID 29736411, 2018). "We hypothesized that the respiratory symptoms observed in patients in cohort 4 may be indicative of ‘on-target off-tumour’ MFEζ T cell binding to CEACAM5 antigen present within the lung which would be consistent with the affinity (2.5 nM) of the MFE23 scFV augmented by avidity in CAR T format." (PMID 28660319, 2017). "In addition, we could demonstrate that 42 in all of 80 tumor samples, CEACAM5 and OPN are being colocalized in cytoplasm by using double-labeling immunohistochemistry." (PMID 22738781, 2012). "Meanwhile, tissue immunofluorescence staining provides direct validation of CEACAM5 expression at the cellular level, while serum CEA testing offers a noninvasive surrogate for monitoring tumor CEACAM5 status." (PMID 40746825, 2025). "Biodistribution and binding specificity of 99mTc-radiolabeled 6B11 was tested in A549 CEACAM5 overexpressing (A549-CEA5-OV) and knockout (A549-CEA5-KO) tumor-bearing mice upon SPECT/CT imaging, γ-counting and autoradiography." (PMID 40358697, 2025). "Carcinoembryonic antigen-related cell adhesion molecule 5 (CEACAM5) was an early target of immunotherapeutic investigation and was of interest due to its role in adhesion and invasion of tumor cells." (PMID 40160238, 2025). "For example, CEACAM5 expressed by tumor cells can interact with CEACAM1 expressed by NK cells and lead to the inhibition of NK cell-mediated tumor target cell killing." (PMID 41283511, 2025). "Next-generation concepts-bispecific CEACAM5/6 ADCs (e.g., CT109-SN-38) and single-domain (VHH) ADCs to boost tumor penetration-are advancing preclinically." (PMID 41256852, 2025). "The human carcinoembryonic antigen (CEA), also known as CEACAM5, is an attractive target due to its well-defined nature as a tumor antigen." (PMID 39766041, 2024). "CAR-M targeting CD19, CD22, HER-2, CD5, and carcinoembryonic antigen-related cell adhesion molecule 5 (CEACAM5) have been developed to fight against solid tumors and hematopoietic malignancies with improved tumor control and significant activation of TME." (PMID 38195534, 2024). "Carcinoembryonic antigen-related cell adhesion molecule 5 (CEACAM5), as a typical tumor marker, has been found to exert immunomodulatory effects in many diseases." (PMID 38686388, 2024). "Select genes including ALDH3B1, CEACAM5, IL8, PYGO2, and WWTR1, exhibited pronounced activity in promoting tumor formation and establishing gene dependencies critical for tumorigenicity." (PMID 38851782, 2024). "Carcinoembryonic antigen-related cell adhesion molecule 5 (CEACAM5) is a transmembrane glycoprotein that is involved in cell adhesion and migration and is upregulated in different tumor types." (PMID 39796075, 2024). "Carcinoembryonic antigen (CEACAM5), as a broad-spectrum tumor biomarker, plays a crucial role in analyzing the therapeutic efficacy and progression of cancer." (PMID 38275310, 2024).
tumor (continued). "CEACAM1, CEACAM5, and CEACAM6 all have variable roles in tumor initiation, progression, and metastasis." (PMID 36741860, 2023). "One approach is tumor-targeting, covering both heme malignancies (CD19) and solid tumors (PD-L1, Her2, FAP, EGFR, PSMA, Cldn18.2, Nectin 4, B7H4, CEACAM5, 5T4, EphA2)." (PMID 37662949, 2023). "The antibody component of SAR408701 binds to the extracellular domain of CEACAM5, initiating the internalization of the ADC into the tumor cell, followed by the subsequent release of DM4 within the cytoplasm." (PMID 38001628, 2023). "Bi-specific antibodies designed to bind 4-1BB and a tumor antigen simultaneously, such as Her2, EGFR, or CEACAM5, should result in the selective activation of 4-1BB pathways in the TME." (PMID 37662949, 2023). "To further examine the therapeutic potentials of our CAR-T cells in vivo, we utilized mouse xenograft tumor models of CEACAM5-expressing DM4S (A549-CEACAM5), DM4R (H1975-CEACAM5) and CEACAM5-negative DM4S (A549) NSCLCs." (PMID 36923424, 2023). "CEACAM5 binds to TGF-β type I receptor (TBR1) with decreased expression of SMAD3 targets, indicating that CEACAM5 can directly inhibit the tumor suppressive properties of TGF-β." (PMID 36741860, 2023). "Taken together, the detection of CEACAM5 and HMGB3 by real-time PCR was suitable for sample prescreening before single-cell or nuclear sequencing experiments requiring the presence of tumor cells." (PMID 36397035, 2022). "NEO-201 can exert a significant anti-tumor activity not only by inducing NK mediated ADCC or CDC, but also enhancing direct NK killing against CEACAM5+/NEO-201+ human carcinoma cells." (PMID 35804808, 2022). "The first consisted of CEACAM5 and CEACAM6 expressing tumour cells, colonic stem cells with high expression of OLFM4 and HIST1H4C." (PMID 35860583, 2022). "Among the four candidate genes, CEA cell adhesion molecule 5 (CEACAM5) and high mobility group box 3 (HMGB3) distinguished the tumor from normal tissues and recapitulated tumor cellularity in single-cell transcriptome data." (PMID 36397035, 2022). "Among the CEACAM family members, CEACAM-5 (CEA) and CEACAM-6 (NCA) play significant roles in tumor progression and metastasis." (PMID 35804808, 2022). "The CEACAM5, HMGB3, and ASS1 genes were specifically expressed in tumor cells from the tumor sample groups (tLung, tL/B, mLN, and mBrain)." (PMID 36397035, 2022). "Based on these results, we recommend sample prescreening using multigene real-time PCR for beta-actin (ACTB), CEACAM5, and HMGB3 to ensure the presence of tumor cells." (PMID 36397035, 2022). "Despite extremely high tumor heterogeneity, malignant cell markers such as MUC1, CEACAM5, S100A11, CD24, and TM4SF1 were relatively uniformly upregulated in cancer cells and had the potential to serve as targets for SBA diagnosis and treatment." (PMID 36104333, 2022). "To apply the prescreening process as a single-tube reaction, we performed multiplex RT-PCR analyses using CEACAM5, HMGB3, and ACTB probes with different fluorescence dye formats, which resulted in consistent tumor-specific detection." (PMID 36397035, 2022). "In contrast, mEPCs from CC1 and GBC11 displayed upregulation of multiple tumor-specific genes (e.g., S100P, TSPAN1, CEACAM5)." (PMID 36198671, 2022). "The difference between CEACAM5-TCB vs. cibisatamab treatment at a dose of 2.5 mg/kg was not significant in that study (p = 0.8) and both showed very strong anti-tumour effect with a lower mean AUCE of 16,042 mm3/h in case of CEACAM5-TCB." (PMID 34959386, 2021). "We investigated the impact of LN tissue volume examined for detection of tumor cells using CEACAM5 mRNA levels as a proxy for tumor cell amounts, and KLK6 and SLC35D3 mRNAs as proxies for tumor cell aggressiveness." (PMID 34192710, 2021).
tumor (continued). "The mAb NEO-201 with selective CEACAM5 and CEACAM6 targeting capacity and anti-tumour activity showed strong immunoreactivity in a cohort of MOC samples and other tumour types with minimal cross-reactivity to surrounding normal tissue." (PMID 34830751, 2021). "We also detected uniquely in C3N-02671 tumor tissue two protHLAIp TAAs (CCND1 and PXDNL) and five protHLAIIp TAAs (MMP2 and CEACAM5)." (PMID 32157095, 2020). "Pretargeted immuno-PET has been developed against different antigens, and promising results have been reported in tumor expressing carcinoembryonic antigen (CEA; CEACAM5) using a bispecific mAb (BsmAb) and a radiolabeled peptide." (PMID 31214593, 2019). "Part of them have been documented to be tumor promoter genes of PC, such as GABRP, CEACAM5, CEACAM6 and CST1." (PMID 31706267, 2019). "Collectively, these data indicated that upregulation of CEACAM5 expression in metastatic lesions induces MET and enhances the outgrowth of metastatic tumor cells in secondary sites." (PMID 29736411, 2018). "We found that CEACAM1, CEACAM5 and CEACAM6 are present on tumor-derived MVs, and that human and murine endothelial cells release CEACAM1 expressing MVs." (PMID 24040308, 2013). "Thorough validation in clinical samples revealed that KRT19, CEACAM5, SFTPA, SFTPC and DSG3 were promising markers for tumor cells in LNs and PB from NSCLC patients." (PMID 23671585, 2013). "KRT19, CEACAM5 and EPCAM mRNA had been reported previously as promising tumor cell markers in LNs from NSCLC patients, whereas SFTPA and SFTPC were novel genes in this context." (PMID 23671585, 2013). "In this study, we reported a novel anti-CEACAM5 mAb CC4, which has striking capabilities of both targeting and accumulating in tumor tissues in vivo and remarkable functions of inhibiting tumor growth in animal models." (PMID 21731662, 2011). "In the present study, we provide new insights into the multiplicity and diversity of CEACAM1, CEACAM5 and CEACAM6 expression and their functions in tumor development and progression." (PMID 20090913, 2010). "CEACAM5 and CEACAM6 are commonly considered inert tumour markers, despite the discovery and documentation of their tumorigenic functions over the past two decades." (PMID 17576469, 2007). "We confirmed that CEACAM5 expression was localized in organoids derived from tumor tissue and not, or to a lesser extent, in organoids derived from healthy gastric tissue." (PMID 40868067, 2025). "We observed a trend of increasing CEACAM5 expression with advancing tumor stage, although the difference was not statistically significant." (PMID 40868067, 2025). "CEACAM5, upregulated under hypoxic conditions via HIF1α, activates the MAPK/ERK pathway in TAMs, leading to M2 polarization and increased extracellular matrix degradation through MMP9, which facilitates tumor cell migration and invasion." (PMID 40303340, 2025). "In patients who did not undergo perioperative chemotherapy, CEACAM5 expression was better preserved within the tumor, facilitating its detection." (PMID 40868067, 2025). "The in vivo anti-tumor activity of NILK-2401 was investigated in a mouse xenograft model, using SNU-C1 as target cells, as well as in a syngeneic model using human SIRPα/human CD47 transgenic mice with MC38 transfected with human CEACAM5 and human CD47." (PMID 38720892, 2024). "In contrast, CEACAM5 expression was detected in normal tissue as well as tumor tissue from the colon, and no CEACAM5 was observed in normal and tumor of other tissues." (PMID 36923424, 2023). "After its identification as a tumor-specific marker for colorectal cancer in 1965 by Gold and Freedman, the carcinoembryonic antigen (CEA), later classified as CEACAM5, was the first of a wide family of CEACAMs to be discovered as important regulators in carcinogenesis." (PMID 36891299, 2023).
tumor (continued). "While one sample did not respond to any of the conditions, although CEACAM5 was highly expressed, a favorable effect of NILK-2301 was observed in the overall tumor fraction independent of CEACAM5." (PMID 38087365, 2023). "Across the six ductal cell subclusters, we observed an opposite trend of gene expression between proliferating markers (e.g., MKI67) and malignant metastatic markers (e.g., CEACAM5/6 and KLK7), suggestive of orchestrated differentiation of tumor cells during metastasis." (PMID 37612267, 2023). "After 48 h, NILK-2301 induced dose-dependent killing of all CEACAM5-positive cell lines regardless of tumor type as determined by LDH release, with half maximum effective concentrations (EC50) ranging from 0.008 nM (H2122) to 0.15 nM (H508)." (PMID 38087365, 2023). "Both of these cell populations exhibit distinctive oncogenic cell–cell adhesion molecules, such as carcinoembryonic antigen-related cell adhesion molecule 5 (CEACAM5) and CEACAM6, which could result in increased tumor cell cluster formation and metastasis." (PMID 35892569, 2022). "For instance, GBC9-MT showed elevated expression of CD24 (immune checkpoint in promoting immune evasion) and IGFBP2 (metabolic checkpoint in promoting tumor growth), and GBC10-MT displayed cancer stem cell signature (OLFM4) and enhanced cell migration (e.g., CLDN3, CEACAM5)." (PMID 36198671, 2022). "TRIB3 and FABP1 may interact with CEACAM5, PRAP1, GABRP and THBS4, and affect tumor immune microenvironment by regulating immune cells, and participate in the development and progression of GC." (PMID 34957220, 2021). "Bioinformatics analysis showed that TRIB3 and FABP1 may interact with CEACAM5, PRAP1, GABRP, and THBS4, and affect tumor immune microenvironment by regulating immune cells, and participate in the development and progression of GC." (PMID 34957220, 2021). "Considering the established oncogenic roles of CEACAM5, it is reasonable to speculate that SMOC2-induced CEACAM5 down-regulation may contribute to a tumor suppressive role of SMOC2 in CRC progression." (PMID 32884102, 2020). "Even if CEACAM5-positive cells are less invasive per se this does not leave out a role for CEACAM5 with regard to other processes of tumor dissemination when considering formation of metastases." (PMID 33196697, 2020). "Due to low sample numbers, we were not able to statistically evaluate differences in CEACAM5 expression for metastatic/recurrent tumor samples, though CEACAM5 expression in these tissues was qualitatively similar to primary tumor tissues." (PMID 33004987, 2020). "Next, MethylMix-PA identified hypo-methylation of CEACAM5 (also known as CEA), a cell surface glycoprotein that is used as a clinical biomarker for gastrointestinal cancers and may promote tumor development through its role as a cell adhesion molecule." (PMID 31356589, 2019). "In addition, DCISCAF2cy markedly up-regulated expressions of carcinoembryonic antigen-related cell adhesion molecule 5 (CEACAM5; CAM5) and CEACAM6 (CAM6), tumor-promoting cell–cell adhesion molecules." (PMID 31331982, 2019). "Our data demonstrate that CEACAM5 has a role in this process and suggest that perturbation of MET programs may be a therapeutic strategy to restrain tumor outgrowth at the metastatic site." (PMID 29736411, 2018). "Although evidence for the presence of CEACAM5 in tumor derived MVs has been previously reported, no thorough analysis on CEACAMs in MVs has been published." (PMID 24040308, 2013). "CEACAM5 and OPN are colocalized in cytoplasm, and a significant correlation was observed between the positive colocalization and the negative colocalization in the depth of invasion and the differentiation of the tumor." (PMID 22738781, 2012). "The findings demonstrated that the transformation of CEACAM5 expression pattern and colocalization with OPN might play a critical role in tumor metastasis and invasion." (PMID 22738781, 2012).
tumor (continued). "Identification of CEACAM1 as a MHC-I-independent NK inhibitory receptors provided new insights toward understanding tumor immune evasion mechanisms, since the binding partners of CEACAM1—CEACAM1 itself and CEACAM5—are widely present in various types of cancers." (PMID 21731662, 2011). "Finally, CD44, CD166, CD29, CEACAM5, cadherin 17, and biglycan were identified by mass spectrometry to be enriched in CD133+ tumour spheroid cells." (PMID 20332776, 2010). "In this work, we evaluated CEACAM5 and CEACAM6 as a function of tumor cell differentiation." (PMID 17201906, 2007). "With growing knowledge of the effects of CEACAM5 and CEACAM6 on tumour biology, novel therapeutic strategies that focus more on perturbing the tumorigenic functions of these antigens may now be indicated." (PMID 17576469, 2007). "For all tumor cores evaluated, the amount of CEACAM6 was greater than that of CEACAM5." (PMID 17201906, 2007). "However, the results in this study are the first to explore differences in both CEACAM5 and CEACAM6 as a function of tumor histotype across six tumor tissues." (PMID 17201906, 2007). "When the anti-CEACAM5 ADC SAR408701 showed limited efficacy or resistance, CAR-T cells targeting the same antigen could still effectively induce cytotoxic responses and significantly inhibit tumor growth in vivo." (PMID 40843358, 2025). "NILK-2401 is a fully human BsAb binding the CEACAM5 N-terminal domain on tumor cells by its lambda light chain arm with an affinity of ≈4 nM and CD47 with its kappa chain arm with an intendedly low affinity of ≈500 nM to enabling tumor-specific blockade of the CD47-SIRPα interaction." (PMID 38720892, 2024). "Also, ADCP of CEACAM5+/CD47+ tumor cells induced by NILK-2401 was not impacted by the presence of a CD47 sink (i.e., presence of CD47-positive RBCs)." (PMID 38720892, 2024). "However, not all tumor parts had decreased CEACAM5 promoter methylation levels than the paired normal samples." (PMID 37942534, 2024). "No clear correlation between EC50 and CEACAM5-density on tumor cells was observed (R2 = 0.00122)." (PMID 38720892, 2024). "Among the three potential candidates TROP2, CEACAM5 and CD138 that were analyzed further, TROP2 shows the most promising protein expression as it shows a high protein expression over all tumor stages and might even be an interesting therapeutic candidate for earlier stages." (PMID 38730739, 2024). "Therefore, the LYZ, LCN2, CEACAM5, and AGRN genes, with specific expression along the malignant continuum, may serve as markers for CRC precancerous diagnosis and tumor progression detection." (PMID 39456726, 2024). "Some tumor areas showed overlap between CEACAM5 and CEACAM6, but this was not always the case." (PMID 38502695, 2024). "CEA, also known as carcinoembryonic antigen–related cell adhesion molecule 5 (CEACAM5) or CD66e, is a 180 to 200 kDa protein belonging to the CEACAM superfamily that is anchored to the cell surface via glycosylphosphatidylinositol (GPI), It is often highly expressed in various tumor entities." (PMID 36341333, 2022). "Furthermore, both HL-60 and U937 do not express CEACAM5 and CEACAM6, suggesting that NEO-201 can bind to core 1 and extended core 1 O-glycans attached to any tumor-associated protein containing the amino acids serine and threonine." (PMID 36291783, 2022). "However, a notable subset of sample sets demonstrated intratumoral heterogeneity in the primary tumor, the metastatic lesion or both, suggesting that both CEACAM5-positive and –negative cells can play a role in tumor dissemination." (PMID 33196697, 2020). "However, in nude mice, TF2 binding is limited to the grafted human tumor cells, because normal mouse organs do not express human CEACAM5." (PMID 29938001, 2018).